IL17RA (interleukin 17 receptor A)
Diseases named in the same sentence as IL17RA in open-access papers (continued):
Sharing a sentence is not in itself a finding about the gene and the disease.
renal fibrosis (5 papers, 2014 to 2025). A final common manifestation of a wide variety of chronic kidney diseases characterized by glomerulosclerosis and tubulointerstitial fibrosis. "Investigations in renal fibrosis reveal a role for IL-17RA as a novel modulator of monocyte phenotype and polarisation towards tissue macrophages and thus potentially tissue remodelling." (PMID 27263531, 2016). "Il17ra appears to be a novel modulator of monocyte phenotype and possible therapeutic target in renal fibrosis." (PMID 24454873, 2014). "We investigated the effect of Il17ra on myeloid cells in renal fibrosis and found a decrease in Il17ra-/- macrophages in direct comparison of wt and Il17ra-/- cells in mixed chimeric mice." (PMID 24454873, 2014). "Furthermore, interleukin 17 receptor A (IL-17RA) is involved in KTRMs-mediated renal fibrosis, which not only recruits the innate immune cells through the IL-17/IL-17RA signaling pathway but also influences the formation of tissue macrophages." (PMID 40230850, 2025). "Blocking IL-17RA present on the surface of bone marrow cells could relieve renal fibrosis." (PMID 33391465, 2021). "In the absence of Il17ra on all myeloid cells, renal fibrosis was significantly attenuated." (PMID 24454873, 2014).
sarcoidosis (5 papers, 2018 to 2022). Sarcoidosis is a multisystemic disorder of unknown cause characterized by the formation of immune granulomas in involved organs. "Taken together, our data suggest a functional and pathogenic link between EPHA2, KALRN and IL17RA in the occurrence of the disease of family X sarcoidosis patients, acting in addition to the NOD2 functional defect." (PMID 29554915, 2018). "Recent genetic study showed IL-17RA mutation in association with familial sarcoidosis." (PMID 35048206, 2022). "SARS-CoV2 ORF8 host targets belonging to the sarcoidosis gene panel (IL17RA, EMC1, PLD3, GDF15, FKBP10, ADAM9, and PLAT) highlight significant pathways related to sarcoidosis pathogenesis." (PMID 34440765, 2021). "Remarkably, in addition to NOD2 2722G > C, three single nucleotide variants for the IL17RA, KALRN and EPHA2 genes were found in the family X patients with sarcoidosis." (PMID 29554915, 2018). "Moreover, some proteins in Class 1, including IL17RA, growth differentiation factor 15, FK506-binding protein 10, and PLAT, are associated with sarcoidosis pathogenesis." (PMID 35178414, 2022). "Our finding further establishes that the NOD2 2722G > C variant in combination with variants for IL17RA, EPHA2 and KALRN genes could play a significant role in the development of sarcoidosis." (PMID 29554915, 2018). "Combination of polymorphisms in the NOD2, IL17RA, EPHA2 and KALRN genes could play a significant role in the development of sarcoidosis by maintaining a chronic pro-inflammatory status in macrophages." (PMID 29554915, 2018).
viral infection (5 papers, 2015 to 2025). "IL-17RA signaling is also involved in the pathogenesis of acute respiratory distress syndrome (ARDS) caused by viral infection." (PMID 34819358, 2022).
fibrosis (4 papers, 2018 to 2025). the formation of excess fibrous connective tissue in an organ or tissue in a reparative or reactive process. "In consequence, we drew the preliminary conclusion that ADSC-Exo attenuated hypertrophic scar fibrosis by miR-192-5p/IL-17RA/Smad axis." (PMID 33789737, 2021). "Similar results were observed at the protein level, where IL17A protein was almost absent in normal and paraffin oil control groups of liver tissue while the tissue derived from CCl4-induced fibrosis group and recovery group showed high degree of expression of IL-17A and IL17RA proteins." (PMID 30346985, 2018).
Hypertension (4 papers, 2018 to 2024). The presence of chronic increased pressure in the systemic arterial system. "IL17RA has been linked to myocardial collagen metabolism in hypertension-induced diastolic dysfunction and heart failure." (PMID 29556499, 2018). "Blockage of AT1R or IL-17RA signaling, on the contrary, improves vasodilation and neurovascular coupling in long-term hypertension." (PMID 39495252, 2024). "Recently, we demonstrated in a DOCA-salt model of hypertension that dural T-cell-derived IL-17 generates ROS production in BAMs via IL-17RA, which impairs neurovascular coupling and also leads to cognitive impairment." (PMID 38613621, 2024). "On the cellular level, angiotensin II (Ang-II)/Ang-II receptor type 1 (AT1R) or IL-17/IL-17RA signaling reduces endothelial NO bioavailability, impairing endothelial-mediated vasodilation in salt-sensitive and Ang-II-induced hypertension." (PMID 39495252, 2024). "The IL-17A/IL-17RA axis in the brain may represent a novel therapeutic target for cardiovascular diseases such as HF and hypertension." (PMID 36312009, 2022).
ileitis (4 papers, 2013 to 2024). "However, according to reports in the literature, mice with signaling receptor IL-17RA deficiency show reduced ileitis and inflammation in other organs and prolonged survival." (PMID 33287313, 2020). "Moreover, an enhanced Th17 response with elevated IL-17A and IL-22 expression has been reported upon T. gondii infection with diminished ileitis in IL-17RA and IL-22 deficient mice." (PMID 31057534, 2019).
lung carcinoma (4 papers, 2022 to 2024). "Several clinical studies have demonstrated an essential role of both IL-17RA and IL-17RC in cancer progression, including prostatic and lung cancer and GC." (PMID 36125689, 2023). "High expression of the BC-specific ICD-derived metagene signature (TNF/CXCR3/P2RX7/CASP1/NLRP3/IL1B/LY96/CD4+/CD8+A/CD8+B/PRF1/IFNG/IL17A/IL17RA) is associated with prolonged overall survival (OS) in BC and OC patients but not in lung cancer patients." (PMID 37445860, 2023).
colorectal tumors (3 papers, 2015 to 2024). "To assess the expression levels of IL‐17RA in colorectal tumors, we examined the expression of IL‐17RA in human CRC and adjacent normal tissues using IHC staining and qRT‐PCR." (PMID 38491831, 2024). "One study reported that the IL-17 receptor A (IL-17RA) was expressed on transformed epithelial cells and these developed into colorectal tumours." (PMID 26101460, 2015).
Hepatic steatosis (3 papers, 2021 to 2023). Steatosis is a term used to denote lipid accumulation within hepatocytes. "In an analysis using mice, IL-17A-, IL-17F-, and IL-17RA-deficient mice showed liver steatosis in a fatty liver model due to a methionine choline-deficient diet, but the degree of liver dysfunction was significantly lower than that of wild-type mice." (PMID 33918456, 2021). "As a tumor-promoting cytokine, IL-17A can regulate alcohol-induced hepatic steatosis, inflammation, fibrosis and HCC, and the development of HCC in alcohol-fed mice was suppressed by deleting the IL-17RA gene." (PMID 36998605, 2023).
myeloma (3 papers, 2018 to 2024). "Concerning the relationship between IL-17 serum levels and the MM patient’s survival and therapeutic response, the possible mechanisms are that elevated IL-17 produced by Th17 cells promotes myeloma cell growth and inhibits immune function by IL-17A receptor (IL-17RA) expressed on tumor cells." (PMID 36119497, 2022). "As the role of IL-5 as growth factor for myeloma plasma cells is debated, and IL-5 should not impact on BM stromal cells, one mechanism by which anti-IL17, anti-IL-17RA, and anti-IL5 antibodies acted in Vk*MYC mice is a reduced accrual and survival of eosinophils and consequently of Th17 cells." (PMID 30510245, 2018).
oral cancer (3 papers, 2017 to 2023). "In addition, the study shows that C. albicans-induced IL-17A/IL-17RA signaling promotes the growth of oral cancer xenografts in vivo." (PMID 37374978, 2023). "Consequently, the increased IL-17A/IL-17RA signaling activates macrophages and promotes the release of inflammatory cytokines, which in turn enhances the proliferation, migration, and invasion of oral cancer cells." (PMID 37374978, 2023). "In conclusion, CMP and its ingredient cordycepin can inhibit tumor growth and malignant transformation in a mouse model for oral cancer via inhibition of EGFR- and IL-17RA-signaling and enhancement of anti-tumor immunity." (PMID 29212184, 2017).
spondyloarthritis (3 papers, 2016 to 2024). "IL-17A and IL-17F together with their coreceptor (IL-17RA/RC) were reported to play a significant role in the pathogenesis of spondyloarthritis." (PMID 34744511, 2021). "Blockade of IL-17A or IL-17RA is a promising therapeutic approach in patients with spondyloarthritis, as it decreases IL-17-induced inflammation." (PMID 27165410, 2016).
Stroke (3 papers, 2019 to 2025). Sudden impairment of blood flow to a part of the brain due to occlusion or rupture of an artery to the brain. "IL-17A and its receptor IL-17RA are involved in post-stroke inflammation and disruption of the BBB." (PMID 40289984, 2025). "Therefore, the IL-17A/IL-17RA pathway induces the formation of M1 microglia after stroke." (PMID 40289984, 2025).
Trypanosoma cruzi Infection (3 papers, 2012 to 2020). "IL-6 improves the cytotoxic CD8+ T cell dysfunction triggered by nitric oxide in patients with Chagas disease; additionally, we recently demonstrated that IL-17RA and IL-17A are critical factors for sustaining CD8+ T cell immunity to T. cruzi." (PMID 32398312, 2020). "The absence of IL-17RA and IL-17A/F during Trypanosoma cruzi infection resulted in increased tissue parasitism and reduced frequency of parasite-specific CD8+ T cells." (PMID 30364284, 2018).
type 1 diabetes (3 papers, 2020 to 2025). "Associations of IL-17RA variants with pancreatic autoantibodies in patients with type 1 diabetes." (PMID 40979706, 2025). "In addition, findings suggest that genetic variants in the IL17RA and IL21R genes are associated with the development of Type 1 Diabetes (T1D) and the production of pancreatic and extra-pancreatic autoantibodies." (PMID 40979706, 2025).
ulcerative colitis (3 papers, 2024 to 2025). An inflammatory bowel disease involving the mucosal surface of the large intestine and rectum. "A recent study has demonstrated that Gingerenone A, a phenolic compound isolated from Zingiber officinale, is able to improve intestinal mucosal inflammation and restore intestinal barrier homeostasis by inhibiting IL-17RA signaling to ameliorate ulcerative colitis (UC)." (PMID 40055805, 2025).
allergic asthma (2 papers, 2022 to 2025). A asthma with a basis in a pathological type I hypersensitivity reaction. "IL-17E (IL-25) is key to regulating type 2 immune responses and driving inflammatory conditions like allergic asthma through IL-17RA and IL-17RB receptors." (PMID 40443529, 2025). "IL-17E (also known as IL-25) is a key regulator of type 2 immune responses and driver of inflammatory diseases, such as allergic asthma, and requires both IL-17 receptor A (IL-17RA) and IL-17RB to elicit functional responses." (PMID 35863378, 2022).
Anxiety (2 papers, 2022 to 2023). Intense feelings of nervousness, tension, or panic often arise in response to interpersonal stresses. "IL-17 promotes anxiety development through neuronal IL-17A receptor (IL-17Ra) signaling in the medial prefrontal cortex." (PMID 37273529, 2023).
cerebral malaria (2 papers, 2021 to 2024). A sequestration of Plasmodium falciparum in the brain, which can cause coma and/or seizures. "Variants in IL17F and IL17RA have been found associated with cerebral malaria and similar variation may contribute to the outcome of schistosome infection." (PMID 33659002, 2021).
depression (2 papers, 2023 to 2025). "An epigenetic meta-analysis on MDD suggests that IL17RA plays a role in the neurobiological mechanisms of depression, likely through inflammation." (PMID 40370590, 2025). "IL17A/IL-17RA signaling activated by psoriatic inflammation in the brain mediates downstream inflammatory effects required for depression." (PMID 38046578, 2023). "In this study, functional enrichment analysis revealed that targets such as CD63, IL17RA, and IL1R1 are involved in depression-related pathways, including the HIF-1, MAPK, and PI3K-Akt signaling pathways." (PMID 40370590, 2025). "Although several potential drugs targeting CD63, IL17RA, and IL1R1 were identified, limited research exists on their effects on MDD or depression." (PMID 40370590, 2025).
disseminated candidiasis (2 papers, 2015 to 2016). Systemic candidiasis occurs when Candida yeast enters the bloodstream and may spread (becoming disseminated candidiasis) to other organs, including the central nervous system, kidneys, liver, bones, muscles, joints, spleen, or eyes. "A recent study also suggested a role for IL-17RA signaling in NK cell development in the context of disseminated candidiasis, although this report conflicts with a study showing that NK cells are redundant for antifungal defense in immunocompetent hosts." (PMID 27814401, 2016). "In addition to a critical role in protecting against oral mucosal candidiasis, IL-17RA and IL-17A are protective in an intravenous model of disseminated candidiasis." (PMID 25849644, 2015).
eosinophilia (2 papers, 2008 to 2013). "Experiments in IFN-γ or IL-17RA-deficient mice revealed that IFN-γ was responsible for the inhibition of airway eosinophilia whereas IL-17 was required for the induction of airway neutrophilia." (PMID 23805294, 2013). "In IL-17RA−/− mice addition of eLPS suppressed eosinophilia but did not induce airway neutrophilia." (PMID 23805294, 2013).
Granuloma (2 papers, 2017 to 2022). A compact, organized collection of mature mononuclear phagocytes, which may be but is not necessarily accompanied by accessory features such as necrosis. "Corroborating our previous findings, the Pb18-infected IL-6- and IL-17RA-deficient mice showed diminished capacity to mount organized granulomas at 30 dpi when compared to C57BL/6 group." (PMID 28871251, 2017). "The infected mice in our study showed similar results; however, the IL-17RA-/- 3dpi mice showed an increase in hemoglobin and inflammatory nodular aggregates formed mainly by eosinophils, which later gave rise to granulomas." (PMID 35844540, 2022). "However, the IL-17RA pathway triggers the formation of pulmonary nodular aggregates that suggest a future formation of granulomas that amplify the lung injury." (PMID 35844540, 2022).
heart failure (2 papers, 2017 to 2018). Inability of the heart to pump blood at an adequate rate to meet tissue metabolic requirements. "However, a recent study investigating the role of IL-17A in non-chagasic inflammatory dilalated cardiomyopathy–an important cause of noncongenital heart failure in individuals under the age of 40, has reported that IL-17A/IL-17RA signaling pathway is required for the development of the disease." (PMID 28278264, 2017).
inflammatory skin disease (2 papers, 2020 to 2024). Inflammatory skin disorders covers a broad category that includes many conditions ranging in severity, from mild itching to grave medical health complications These disorders are common in people of all ages and races. "IL-17A and IL-17F are expressed by immune cells and bind to IL-17RC and IL-17RA; their transcriptional regulation and contribution to inflammatory skin diseases are well understood." (PMID 38470486, 2024).
keloid (2 papers, 2009 to 2022). An irregularly shaped, elevated mark on the skin caused by deposits of excessive amounts of collagen during wound healing. "Two studies found that ASCs EVs could inhibit the proliferation/migration, and promote the apoptosis of keloid/hypertrophic scar fibroblasts via the regulation of miR-192-5p/IL-17RA/Smad axis or inhibiting TGF-β1/Smad pathway." (PMID 35505389, 2022).
latent infection (2 papers, 2021 to 2025). "Interestingly, the frequency of β-lactamase- positive B220+ GL7+ B cells was also decreased approximately sixfold in IL-17RA−/− spleens, indicating that IL-17RA signaling promotes the latent infection of activated/germinal center B cells." (PMID 33824206, 2021).
lung disease (2 papers, 2018 to 2023). "Thus, in the Il17ra KO animals, neutrophil recruitment and activation is attenuated to an extent that ameliorates pulmonary disease, but prevents bacterial escape into the systemic circulation and subsequent severe disease." (PMID 29813133, 2018).
lymph node metastases (2 papers, 2023 to 2025). "We examined the clinical data of 77 patients with PCa and lymph node metastasis (LN+) and then evaluated the levels of IL-17A and IL-17RA expression in the prostate and LN+." (PMID 37760548, 2023).
oral candidiasis (2 papers, 2021 to 2023). Infection of the mucosal lining of the mouth with the fungus Candida albicans. "In the oral cavity specifically, mice lacking IL-17RA in the suprabasal oral mucosae (Il17rafl/fl-K13Cre+) have diminished neutrophil levels, contributing to their high susceptibility to oral candidiasis." (PMID 34220843, 2021).
osteoarthritis (2 papers, 2020 to 2023). A noninflammatory degenerative joint disease occurring chiefly in older persons, characterized by degeneration of the articular cartilage, hypertrophy of bone at the margins and changes in the synovial membrane. "Therefore, aptamers blocking IL-17/IL17RA interactions show promise as potential therapeutics for osteoarthritis and probably other IL-17 rheumatic disorders." (PMID 33266394, 2020). "Experiments on osteoarthritis mice showed that intra-articular injections of RA10-6 inhibit synovial inflammation by blocking IL-17/IL17RA-mediated IL-6 expression and did not induce systemic or immunotoxic effects." (PMID 33266394, 2020).
ovarian carcinoma (2 papers, 2025). A malignant neoplasm originating from the surface ovarian epithelium. "In ovarian cancer, lymphoid cells producing IL-17 have been shown to mobilize a distinct subset of small peritoneal macrophages enriched for IL-17RA and protumor mediators, which directly support tumor cell growth." (PMID 41590709, 2025). "By integrating network pharmacology, molecular docking, and molecular dynamics simulations with in vitro validation in ovarian cancer cells and TAMs, we aimed to delineate the dual modulatory actions of these marine secondary metabolites on the IL-17RA/Act1 and ERK1/2 pathways." (PMID 41590709, 2025). "In SKOV3 ovarian cancer cells, phlorotannins suppressed migration and invasion by approximately 40 to 60%, accompanied by reduced MMP expression linked to IL-17RA–Act1 signaling attenuation and by increased TIMP1 expression in association with transient ERK1/2 activation." (PMID 41590709, 2025). "This study demonstrates that phlorotannins from E. cava act as bioactive marine polyphenols that modulate IL-17RA–Act1 and MAPK signaling, suppress ovarian cancer invasion, and reshape the tumor microenvironment." (PMID 41590709, 2025). "Collectively, this study demonstrates that phlorotannins suppress ovarian cancer cell migration and invasion by up to approximately 60% and attenuate pro-metastatic MMP expression and activity through coordinated modulation of IL-17RA/Act1 signaling and early ERK1/2 activation." (PMID 41590709, 2025). "However, the relationship between phlorotannin-mediated IL-17RA modulation and ERK1/2 activation in the context of ovarian cancer has not been fully elucidated." (PMID 41590709, 2025).